HIF1A (hypoxia inducible factor 1 subunit alpha)
Diseases named in the same sentence as HIF1A in open-access papers (continued):
Sharing a sentence is not in itself a finding about the gene and the disease.
angiosarcoma (5 papers, 2010 to 2024). A malignant tumor arising from the endothelial cells of the blood vessels. "Furthermore, we are interested in whether the microenvironment might play a role in these two entities by staining HIF-1α which shows two cases of multifocal intranuclear and one case of both intracytoplasmic and intranuclear positivity in angiosarcoma and negative for all AHs." (PMID 35979530, 2022).
aspergillosis (5 papers, 2014 to 2022). Aspergillosis is an infection, growth, or allergic response caused by the Aspergillus fungus. "An important aspect to notice is that host immune cells need to be able to adequately sense hypoxia by HIF1α to be able to clear Aspergillus as was recently illustrated by an increased susceptibility to aspergillosis when myeloid cells lack HIF1α47." (PMID 27215684, 2016). "Given the phenotype of the HIFC mice, it stands to reason that steroid mediated suppression of HIF1α could contribute to aspergillosis susceptibility." (PMID 25255025, 2014). "Previous reports established HIF-1α as a central regulator of antifungal immunity in the context of aspergillosis." (PMID 36275017, 2022).
atrophic gastritis (5 papers, 2019 to 2025). "Activation of HIF-1α/VEGF angiogenesis pathway promotes the development of MNNG-induced atrophic gastritis." (PMID 37964307, 2023).
bone metastasis (5 papers, 2009 to 2025). Transfer of a neoplasm from its primary site to bones. "Our study showed that HIF-1α predicts poor prognosis since it correlates with bone metastasis which is in turn associated with shorter time to progression." (PMID 31903166, 2019). "In the current analyses, CSPG4 was positively associated with CD34 and HIF1A, together with the previous report on the role of CSPG4 in angiogenesis, CSPG4 tends to be a promising molecule to be evaluated for its involvement in bone metastasis related angiogenesis." (PMID 35685372, 2022). "Considering that HIF-1α is a crucial partner of ASH1L in metastatic cells and agents targeting HIF-1α are currently under clinical investigation, we also evaluated the effects of HIF-1α inhibitor PX-478 in our preclinical model of bone metastasis." (PMID 40394007, 2025). "Patients with bone metastasis harboured higher HIF-1α expression (in both intensity and tumour positive stained cell) than patients without bone metastasis." (PMID 34298636, 2021).
bronchopulmonary dysplasia (5 papers, 2014 to 2024). Bronchopulmonary dysplasia is a chronic respiratory disease that results from complications related to lung injury during the treatment of infant acute respiratory distress syndrome in low-birth-weight premature infants or from abnormal lung development in older infants. "Therefore, the loss of HIF-1α expression may be one of the important reasons for the occurrence of bronchopulmonary dysplasia (BPD) in premature infants." (PMID 39102510, 2024).
cerebrovascular disease (5 papers, 2018 to 2025). "For the cerebrovascular diseases, a higher plasma level of HIF‐1α was associated with a decreased incidence of CES (odds ratio [OR] = 0.885; 95% confidence interval [CI] = 0.796−0.985, p = 0.026) in the IVW method, with a statistical power of 88%." (PMID 40022282, 2025). "This study aimed to test the causality relationship between plasma HIF‐1α and neurological diseases, including cerebrovascular diseases, migraines, and neurodegenerative diseases with a Mendelian randomization (MR) method." (PMID 40022282, 2025). "The expression of HIF-1α is a key event in the pathophysiology of cerebrovascular diseases." (PMID 30622459, 2018).
cervical adenocarcinoma (5 papers, 2015 to 2023). An adenocarcinoma arising from the cervical epithelium. "Hypoxia has been observed to increase triglyceride accumulation in lipid droplets through increased Lipin 1 expression in a HIF-1α dependent mechanism, as shown in HeLaM cervical adenocarcinoma and Huh7 human hepatoblastoma cells." (PMID 26305551, 2015). "For example, GPL biosynthesis pathway were up-regulated in human hepatocarcinoma, cervical adenocarcinoma and embryonic kidney cells, while lysophosphatidic acid acyltransferase β (LPAATβ) and HIF1α were jointly overexpressed to improve cell viability under hypoxia." (PMID 31316482, 2019). "Along with quercetin, luteolin and kaempferol were shown to inhibit HIF-1α phosphorylation and suppress its transcriptional activity by interfering with the MAPK pathway in HeLa cervical adenocarcinoma cells." (PMID 35890106, 2022). "In human cervical adenocarcinoma cells, hypoxia activated PKC-δ led to both increased HIF1α transcription and stability." (PMID 31035382, 2019).
cervical squamous cell carcinoma (5 papers, 2015 to 2024). A squamous cell carcinoma arising from the cervical epithelium. "To further investigate the role of HIF-1α in the migration, invasion, and proliferation of cervical squamous cell carcinoma cells, we performed wound healing assay, Transwell invasion assay, and MTT assay." (PMID 35664561, 2022). "By searching the CC dataset on the UALCAN website, we found that HIF1α was highly expressed in cervical squamous cell carcinoma tissues compared with that in normal cervical epithelial tissues." (PMID 35287356, 2022). "In conclusion, HIF-1α significantly affects the expression of YAP/TAZ in cervical squamous cell carcinoma cells, suggesting that HIF-1α can activate the expression of YAP/TAZ gene downstream of Hippo pathway in cervical cells." (PMID 35664561, 2022). "We transfected cervical squamous cell carcinoma cells with lentivirus for knockdown and overexpression of HIF-1α and screened out successfully transfected knockdown SiHa (HPV+) cells and overexpression C33A (HPV-) cells by flow cytometry screening." (PMID 35664561, 2022). "HIF-1α expression was significantly increased in cervical squamous cell carcinoma compared with CIN and normal cervical tissue." (PMID 35664561, 2022). "To further understand the clinicopathological significance of HIF-1α expression in cervical squamous cell carcinoma, we analyzed the relationship between HIF-1α expression and clinicopathological features of cervical squamous cell carcinoma." (PMID 35664561, 2022). "To determine whether HIF-1α can regulate downstream genes of the Hippo pathway (YAP/TAZ) in cervical squamous cell carcinoma cells, we first constructed stable overexpressing HIF-1α C33a cells (LV-HIF-1α), which initially expressed HIF-1α at a relatively low level." (PMID 35664561, 2022). "The expression levels of HIF-1α, YAP, and TAZ in 30 normal cervical tissues, 58 CIN tissues, and 40 cervical squamous cell carcinoma tissues were detected by immunohistochemistry." (PMID 35664561, 2022). "Firstly, the expression of HIF-1α in cervical normal tissue cells H8, cervical squamous cell carcinoma SiHa (HPV+), and cervical squamous cell carcinoma C33a (HPV-) was detected by QRT-PCR and Western blot." (PMID 35664561, 2022). "The positive expression rates of HIF-1α, YAP, and TAZ in normal cervical tissue group were significantly lower than the CIN group and cervical squamous cell carcinoma group." (PMID 35664561, 2022). "Here, we studied the clinical correlation of HIF-1α and YAP/TAZ expression in normal tissues, cervical intraepithelial neoplasia (CIN), and cervical squamous cell carcinoma (CSCC)." (PMID 35664561, 2022). "The expression of HIF-1α, CA-IX, GLUT-1 and VEGF in cervical squamous cell carcinomas was analyzed immunohistochemically." (PMID 26622782, 2015).
chronic heart failure (5 papers, 2022 to 2025). "When cells experience low oxygen levels (hypoxia) as in congestive heart failure, it triggers the activation of a protein called HIF-1α." (PMID 37629664, 2023). "During chronic hypoxia, the production of reactive oxygen species (ROS) can enhance the stability and increased expression of HIF-1α, further indicating that prolonged stable activation of HIF-1 has a worsening effect in chronic heart failure." (PMID 38164358, 2024). "In some heart disease models, such as congestive heart failure and valvular heart disease, VEGF-A expression showed a positive correlation with the expression of HIF-1α and studies have proved that VEGF-A is one of the downstream targets of HIF-1α indeed." (PMID 35833024, 2022).
chronic lung disease (5 papers, 2017 to 2025). According to the definitions of the American and British Thoracic Societies, including pulmonary functional tests, X-rays, and CT scans for items such as fibrosis, bronchiectasis, bullae, emphysema, nodular or lymphomatous abnormalities. "A major consequence of chronic lung diseases on the lung epithelium is hypoxia, driven by airway obstruction, mucus accumulation, structural remodelling and increased HIF-1α activation due to neutrophilic inflammation, all of which impair oxygen delivery to epithelial cells." (PMID 40590703, 2025). "Thus, it is reasonable that preterm infants with chronic lung disease experiencing many episodes of IH will have elevated levels of VEGF via HIF1α upregulation." (PMID 28770109, 2017).
congenital heart disease (5 papers, 2015 to 2025). A heart disease that is present at birth. "Clinical research found that hypoxia activates the myocardial regulating the adaptive metabolic program to maintain the energy demands between cardiac glycolytic metabolism and redox homeostasis by accumulating HIF-1α in patients with cyanotic congenital heart disease." (PMID 36600948, 2022). "Understanding the role of the mitochondria and HIF-1α in the mechanotransductive pathways driving chronic lymphatic vascular abnormalities could lead to innovative therapeutic strategies for children with congenital heart disease and other disorders of lymphatic function." (PMID 33446832, 2021). "Examination of thymus tissue isolated from pediatric congenital heart disease patients has demonstrated that Hif1a expression is low in thymi from acyanotic patients (consistent with the low/absent Hif1a expression we observe in mouse TECs) but strongly induced in the thymus of cyanotic patients." (PMID 39040069, 2024).
endometrioid carcinoma (5 papers, 2008 to 2024). "The association between the expression of GLUT-1 and HIF-1α and histological grade in endometrioid adenocarcinoma was analyzed based on the TMA cores." (PMID 39202223, 2024). "In postmenopausal women, HIF-1α was increasingly overexpressed from inactive endometrium through hyperplasia to endometrioid carcinoma, paralleled by activation of its downstream genes such as CAIX, Glut-1, VEGF, and increased angiogenesis." (PMID 20169098, 2010). "HIF-1α was increasingly expressed from early stages through advanced stages of endometrioid adenocarcinoma, paralleled by activation of its downstream genes, such as GLUT1, vascular endothelial growth factor (VEGF) and increased angiogenesis." (PMID 19619276, 2009). "Perinecrotic, chronic hypoxia-associated HIF-1α expression was absent in inactive endometrium, rare in endometrial hyperplasia, and frequent in endometrioid carcinoma." (PMID 20169098, 2010). "There was a significant correlation between microvessel density and HIF1A expression in non-myoinvasive endometrioid carcinomas as well." (PMID 32210827, 2020).
gynecologic cancer (5 papers, 2015 to 2026). "All 59 studies including 6612 patients explored the association between HIF-1α expression and clinicopathological variables of gynecological cancer." (PMID 25993275, 2015). "Our meta-analysis, which included 6,612 women, demonstrated that the expression of HIF-1α was associated with the clinicopathological characteristics of gynecological cancer." (PMID 25993275, 2015). "We carried out the first meta-analysis to assess the potential association between HIF-1α and the clinicopathological parameters of gynecological cancer." (PMID 25993275, 2015). "Electronic databases including Cochrane Library, PUBMED, Web of Knowledge and clinical trial registries were searched from inception through October 2014 for published, case-control studies assessing the association between HIF-1α and the clinicopathological characteristics of gynecological cancer." (PMID 25993275, 2015). "Studies on HIF-1α regulation of glucose and lipid metabolism and promotion of gynecological malignant tumor progression." (PMID 35800058, 2022). "Despite the limitations of this meta-analysis, we confirmed that HIF-1α is emerging as an important factor in the carcinogenesis of gynecological cancer." (PMID 25993275, 2015). "We demonstrated that the expression of HIF-1α in normal tissue was lower than that in borderline or cancer tissue in gynecological cancer, which is in agreement with previous findings from different studies." (PMID 25993275, 2015). "Quantitative analyses of HIF-1α expression and clinicopathological variables of gynecological cancer." (PMID 25993275, 2015). "Common regulatory hubs across gynecologic cancers include hypoxic conditions, cell-cycle regulators such as the DREAM complex, stemness-associated pathways exemplified by the HIF-1α/PLD2 axis, and stromal cell interactions, notably cancer-associated fibroblast-extracellular matrix crosstalk." (PMID 42220495, 2026). "Thus, further studies included both HIF-1α and other factors are warranted to validate our findings, and to unravel the mechanism of carcinogenesis and progression in gynecological cancer." (PMID 25993275, 2015). "We expect that HIF-1α may serve as a reliable tool for early and accurate prediction of cancer and may be a potential therapeutic target for gynecological cancer." (PMID 25993275, 2015). "HIF-1α may be a facilitator of premalignant progression in gynecological cancer." (PMID 25993275, 2015). "However, the role of hypoxia-inducible factor 1α (HIF-1α) in gynecological cancer remains unclear." (PMID 25993275, 2015). "Following these findings of TM effects on levels of HIF-1α in ECC-1 cells, we studied other gynecologic cancer cells and assessed effects of TM treatment on HIF-1α levels." (PMID 26469226, 2015). "However, results of studies on HIF-1α in gynecological cancer are not always consistent." (PMID 25993275, 2015).
HCMV infection (5 papers, 2017 to 2022). "It is worth noting that hypoxia inducible factor 1 alpha (HIF-1α) expression is induced by HCMV infection." (PMID 36077806, 2022). "HCMV infection using the AD169 or Towne fibroblast-adapted strains increases HIF1α protein levels in the presence of oxygen." (PMID 33758082, 2021). "Cell sensing of HCMV infection increases HIF1α protein levels under conditions with normal oxygen levels (i.e., normoxia)." (PMID 33758082, 2021). "Overall, we discovered a metabolic pathway regulated by HIF1α in HCMV infection in a way that suppressed virus replication." (PMID 33758082, 2021). "Our findings suggest that this observed reduction of IDO1 activity by HCMV infection could be due to a HIF1α-dependent host response to suppress HCMV replication." (PMID 33758082, 2021). "Next, we examined if HCMV infection alters HIF1α activity by measuring the expression of the gene encoding vascular endothelial growth factor (VEGF), which is transcriptionally regulated by HIF1α." (PMID 33758082, 2021). "Hypoxia-inducible factor 1α (HIF1α) is a metabolic regulator that is altered by HCMV infection." (PMID 33758082, 2021). "However, the biological significance of HIF1α in HCMV infection remains unaddressed." (PMID 33758082, 2021). "We find that blocking AhR signaling reduced HCMV replication, suggesting that HIF1α imparts an antiviral effect by decreasing KYN synthesis and AhR activation in HCMV infection." (PMID 33758082, 2021). "The identification of KYN allowed us to define a mechanistic connection between HIF1α, IDO1, and AhR during HCMV infection." (PMID 33758082, 2021). "HCMV infection raises KYN levels, which are suppressed by HIF1α." (PMID 33758082, 2021). "HIF1α protein levels rise in response to HCMV infection in nonhypoxic conditions, but its effect on HCMV replication was not investigated." (PMID 33758082, 2021). "While we found that HIF1α acts as a regulator of metabolism by suppressing KYN levels, the possibility remains that HIF1α may further affect HCMV infection through its other functions." (PMID 33758082, 2021). "In the absence of HIF1α, HCMV infection enhances IDO1 synthesis of KYN." (PMID 33758082, 2021). "Interestingly, non-TNFα treated HK2 KO and HIF1A KO cells showed an increase in HCMV plaque formation relative to the vehicle pretreated control ntg cells, suggesting that HIF1A and HK2 may play a role in restricting HCMV infection that is independent of TNFα signaling." (PMID 35834576, 2022).
Hepatitis (5 papers, 2009 to 2023). Inflammation of the liver. "Taken together, these data indicated that ATF3-mediated mTOR/p70S6K/HIF-1α signaling was crucial for T cell differentiation in IR-triggered liver inflammation." (PMID 30185770, 2018). "Despite the known role of ATF3 in controlling innate inflammatory responses and the involvement of HIF-1α in mTOR signaling, the exact mechanisms by which ATF3 regulates innate immunity and adaptive T cell development in IR-triggered liver inflammation remain largely unknown." (PMID 30185770, 2018).
hypothyroidism (5 papers, 2021 to 2025). Abnormally low levels of thyroid hormone. "Evidence demonstrates that hypothyroidism leads to diminished angiogenic activity, delayed re-epithelialization, and decreased expression of vascular markers such as vascular endothelial growth factor (VEGF) and hypoxia-inducible factor-1α (HIF-1α)." (PMID 41158934, 2025). "An animal study had shown that hypothyroidism decreased the expression of HO-1, GRP78 and C/EBP homologous protein (CHOP) genes/proteins in the mid-gestation while increased the expression of HIF-1α, CHOP and nuclear factor erythroid 2-related factor 2 (NRF2) genes/proteins." (PMID 37810887, 2023). "Daily treatment with Kp-10 did not alter the higher protein expression levels of VEGF, HIF1α, IL10, GRP78, and CHOP caused by hypothyroidism in the junctional zone compared to control, nor the lower expression of Dio2 caused by hypothyroidism." (PMID 35966095, 2022).
intervertebral disc degeneration (5 papers, 2015 to 2025). "The goal of this study was to investigate whether AQP expression is sensitive to intervertebral disc degeneration and if physiological hypoxia and HIF-1α play a role in their regulation in NP cells." (PMID 25844601, 2015). "Although the degeneration mechanisms of intervertebral discs and articular cartilage differ in certain respects, and the patterns of HIF-1α expression are also different, HIF-1α expression also suppresses intervertebral disc degeneration." (PMID 40168275, 2025). "Previous studies indicated that hypoxia-inducible factors (HIF-1α and HIF-2α) are expressed in this tissue and play a role during intervertebral disc degeneration." (PMID 30250404, 2018).